RTL1 (retrotransposon Gag like 1)
Description:
Plays an essential role in capillaries endothelial cells for the maintenance of feto-maternal interface and for development of the placenta.
Synonyms: MAR1; MART1; PEG11; SIRH2; HUR1
Tractability: Antibody: UniProt predicts a signal peptide or a membrane-spanning region. PROTAC: ubiquitination databases record sites on it.
Gene: Protein-coding gene on chromosome 14 (100,879,753 to 100,903,722, reverse strand). Ensembl gene ENSG00000254656.
Subcellular location: Membrane
Subcellular location (Human Protein Atlas): Cytosol
Gene Ontology:
Biological process: placenta development; skeletal muscle tissue development
Cellular component: membrane
Genetic constraint (gnomAD): Loss-of-function variants: 0 observed, 0.27 expected, observed/expected ratio (o/e) 0, 90% interval 0 to 1.87. That is too few expected variants to judge how well the gene tolerates losing a copy. Missense variants: 1,681 observed, 1,828.6 expected, observed/expected ratio (o/e) 0.92, 90% interval 0.88 to 0.96. Synonymous variants: 727 observed, 777.58 expected, observed/expected ratio (o/e) 0.93, 90% interval 0.88 to 0.99.
Homologues: Orthologues: chimpanzee RTL1 (99% identical), macaque RTL1 (96% identical), dog RTL1 (75% identical), pig RTL1 (74% identical), mouse Peg10 (5% identical). Paralogues in human: PEG10 (11% identical), RTL5 (8% identical), RTL4 (6% identical), RTL3 (5% identical), RTL10 (3% identical), RTL6 (3% identical), LDOC1 (3% identical), RTL8A (3% identical), RTL8B (3% identical), RTL8C (2% identical).
Diseases named in the same sentence as RTL1 in open-access papers:
RTL1 is named in the same sentence as 45 diseases in open-access papers, as found by Europe PMC text mining. Sharing a sentence is not in itself a finding about the gene and the disease. The quoted sentences say what the papers report.
melanoma (9 papers, 2017 to 2024). A malignant, usually aggressive tumor composed of atypical, neoplastic melanocytes. "Highly enriched PEG11/RTL1 was also detected in melanoma tissue, especially in early and lateral growth and melanoma cells in vitro via activation of the Wnt/β-catenin signaling pathway." (PMID 37842090, 2023). "The results showed that knockdown of RTL1 inhibited the proliferation of melanoma cells and arrested the cell cycle transition from the G1 to the S phase, whereas overexpression of RTL1 promoted cell proliferation with cell cycle acceleration in the G1 phase." (PMID 29285312, 2017). "Quantitative real-time PCR (QPCR) analysis confirmed the significantly higher expression of RTL1 in melanoma tissues than in nevus tissues." (PMID 29285312, 2017). "In this study, we provided evidence that RTL1 is highly expressed in human melanoma tissues and that the positive rate in early and horizontal growth melanoma is much higher than in vertical growth and metastasis states." (PMID 29285312, 2017). "Knockdown of RTL1 in melanoma cells resulted in cell proliferation suppression; cell cycle arrest at G1 phase; and down-regulation of E2F1, CYCLIN D1, cyclin-dependent kinase 6 (CDK6) and c-MYC." (PMID 29285312, 2017). "The results of the positive rate in different melanoma phases showed that the expression of RTL1 in early and horizontal growth melanoma was higher than that in the vertical growth and metastasis states." (PMID 29285312, 2017). "The inhibition of the nuclear accumulation of β-Catenin reversed the effects of RTL1 on melanoma cell proliferation, thus indicating that RTL1 promotes melanoma cell proliferation by modulating the Wnt/β-Catenin signalling pathway." (PMID 29285312, 2017). "Here, we found that retrotransposon-like 1 (RTL1) is highly enriched in melanoma tissue, especially in early and horizontal growth tissues." (PMID 29285312, 2017). "We found that both the protein and mRNA levels of RTL1 were significantly higher in melanoma cells than in HaCat cells." (PMID 29285312, 2017). "To explore the exact function of RTL1 in melanoma, we generated lentiviral vectors containing the full-length cDNA and shRNAs targeting RTL1 to overexpress and knockdown RTL1, respectively." (PMID 29285312, 2017). "Tissue array analysis was also used to detect the expression of RTL1 in normal skin, nevus, cutaneous squamous cell carcinoma, basal cell carcinoma, and melanoma." (PMID 29285312, 2017). "A cell counting kit (CCK-8) and flow cytometry assays were used to investigate the role of RTL1 in melanoma." (PMID 29285312, 2017). "To explore the role of RTL1 in melanoma, we examined the expression of RTL1 in the nevus and melanoma, and found that RTL1 was highly expressed in melanoma tissues." (PMID 29285312, 2017). "Together, our results demonstrated that RTL1 promotes melanoma cell proliferation by regulating the Wnt/β-Catenin signalling pathway." (PMID 29285312, 2017). "To further investigate the functional mechanism of RTL1 in regulating cell proliferation in melanoma, we observed the effects of RTL1 on the activation of the Wnt/β-Catenin pathway by using TOP/FOP Flash luciferase reporter gene analysis." (PMID 29285312, 2017). "In the present study, we observed that RTL1 was highly expressed in melanoma tissues, and was critically involved in the proliferation of melanoma cells in vitro and tumour growth in vivo." (PMID 29285312, 2017). "In melanoma, RTL1 promotes cell proliferation through the Wnt/β-Catenin signaling pathway." (PMID 38707901, 2024). "Knockdown of RTL1 in these melanoma cells resulted in suppression of cell proliferation." (PMID 37842090, 2023). "The suppression of RTL1 was found to inhibit the growth of melanoma cells." (PMID 35955961, 2022).
melanoma (continued). "In this study, we found that RTL1 activated the Wnt/β-Catenin pathway, thus suggesting that targeting RTL1 may provide a novel therapeutic target to melanoma patients or those with abnormally activated Wnt/β-Catenin signalling and related drug resistance." (PMID 29285312, 2017). "Further, we found that RTL1 activates the Wnt/β-Catenin signalling pathway by regulating the expression of β-Catenin stabilizing proteins, thus promoting cell cycle progression in melanoma cells." (PMID 29285312, 2017). "Moreover, RTL1 was found to promote the cell cycle transition from the G1 to the S phase and the proliferation of melanoma cells." (PMID 29285312, 2017). "Furthermore, the overexpression and knockdown of β-CATENIN rescued the effects of RTL1 on melanoma cell proliferation and the cell cycle." (PMID 29285312, 2017). "Moreover, overexpression of RTL1 in melanoma cells accelerated cell proliferation, promoted passage of the cell cycle beyond G1 phase, and increased the expression of cell cycle related genes." (PMID 29285312, 2017). "More recently, RTL1 has been introduced as a placenta-specific protein with ectopic expression in cancer, particularly evident in hepatocellular carcinoma (HCC), melanoma, and breast cancer." (PMID 38707901, 2024). "Thus, little is known about whether RTL1 is involved in the development of melanoma." (PMID 29285312, 2017). "RTL1 overexpression activates the Wnt pathway by increasing the levels of DOCK4 and MACF1, both of which enhance the release of β-catenin from the destruction complex and increase the stability of β-catenin in melanoma cells." (PMID 38225934, 2024). "In conclusion, we found that RTL1 is highly expressed in early rather than later stages of human melanoma tissues and that it critically regulates the cell cycle regulation and melanoma cell proliferation." (PMID 29285312, 2017). "Previous studies have shown that RTL1 is involved in several cancers, including lung cancer, squamous cell carcinoma of head and neck, and hepatocellular carcinoma, and the methylation level of RTL1 in melanoma patients is significantly lower than people without cancer." (PMID 29285312, 2017).
hepatocellular carcinoma (5 papers, 2016 to 2024). A malignant tumor that arises from hepatocytes. "By contrast, RTL1 has been documented for its upregulation in hepatocellular carcinoma which suggests that it functions as an oncogene." (PMID 29435129, 2018). "It has been reported that overexpression of PEG11/RTL1 leads to the development of hepatocellular carcinoma (HCC) in mice and that upregulation of PEG11/RTL1 occurs in a considerable proportion of human HCC samples." (PMID 37842090, 2023). "Gene set enrichment analysis (GSEA) signatures showed that Braf, Fign and Rtl1 expression were enriched in hepatocellular carcinoma compared to non-tumorous tissues." (PMID 27792127, 2016).
Anxiety (4 papers, 2022 to 2023). Intense feelings of nervousness, tension, or panic often arise in response to interpersonal stresses. "Rtl1/PEG11 was recently implicated in behaviors relevant to anxiety, depression, fear learning and memory, and social dominance, but we were unable to detect PEG11 expression in the hypothalamus at biologically relevant levels." (PMID 37152245, 2023). "These mice exhibit decreased spontaneous movement, increased anxiety-like behavior, and learning and memory impairments, consistent with the finding that Peg11/Rtl1 regulates the excitability of LC neurons." (PMID 37842090, 2023). "Peg11/Rtl1 Mat- and Pat-KO mice exhibit neurodevelopmental abnormalities corresponding to these expression sites, such as decreased spontaneous movement, increased anxiety-like behavior, and learning and memory impairments." (PMID 37892118, 2023). "The increased anxiety-like behavior and memory impairment are thought to be related to the expression of PEG11/RTL1 in the corpus callosum, hippocampal commissure and medial amygdala nucleus." (PMID 37842090, 2023).
Temple syndromes (4 papers, 2020 to 2025). "This study provides strong support that the loss and overproduction of human RTL1 are the major cause of the muscle symptoms observed in Temple syndrome and Kagami-Ogata syndrome, respectively." (PMID 32878913, 2020). "In addition to RTL8A-C, RTL1 and RTL4 have been implicated in neurodevelopmental disorders, such as Kagami-ogata and Temple syndromes and ASD." (PMID 39875098, 2025). "Therefore, it is clear that combined and differential involvement of DLK1 and RTL1 should be considered when investigating the symptoms of Temple syndrome." (PMID 32878913, 2020). "RTL1/PEG11 plays essential roles in the placenta, muscle and brain and is the major gene responsible for the Kagami-Ogata and Temple syndromes, two genomic imprinting diseases." (PMID 35309133, 2022).
breast carcinoma (3 papers, 2021 to 2024). "Differential expression of PEG11/RTL1 in breast cancer tissues compared to normal breast tissue has been associated with higher malignancy and vascular infiltration." (PMID 37842090, 2023). "Preliminary observations indicate high RTL1 expression in breast cancer cell lines and tissues, correlating significantly with histological grade and vascular invasion." (PMID 38707901, 2024). "PEG11/RTL1 expression levels are significantly higher in breast cancer tissues, and higher levels of RTL1 expression on the cell surface were observed in more invasive breast cancer cell lines." (PMID 37842090, 2023). "Cluster-wide downregulation of MiR-379/656 and anti-Rtl1 cluster suggested that epigenomic features responsible for maintenance of imprinting at DLK1-DIO3 might be disrupted in breast cancer." (PMID 34575183, 2021).
Kagami-Ogata syndrome (3 papers, 2020 to 2024). "Our study clearly demonstrates that RTL1 is of crucial physiological significance because it plays a major role in the maturation and maintenance of fetal muscle fibers; therefore, its loss and overproduction affect the muscle phenotypes of Temple and Kagami-Ogata syndromes, respectively." (PMID 32878913, 2020). "All of these results provide strong evidence that the loss and overproduction of Rtl1 are responsible for the muscle abnormalities observed in the Pat-Rtl1Δ and Mat-Rtl1Δ mice, respectively, as well as the muscle symptoms observed in Temple and Kagami-Ogata syndromes." (PMID 32878913, 2020). "In Kagami-Ogata Syndrome (KOS14), conversely, the loss of MEG3 expression would correlate with increased DLK1 and RTL1 expression, now from both the parental chromosomes." (PMID 38613389, 2024). "This is the first demonstration that an LTR retrotransposon-derived Rtl1 plays an important role in fetal and neonatal muscle development, strongly suggesting the crucial involvement of RTL1 in several muscle symptoms observed in the Temple and Kagami-Ogata syndromes." (PMID 32878913, 2020). "We also demonstrated that the severity of Kagami-Ogata syndrome exhibits good correlation with the degree of RTL1 overexpression but does not have any apparent correlation with the expression levels of DLK1, MIRG or other miRNA clusters." (PMID 32878913, 2020).
neuroblastoma (3 papers, 2019 to 2024). Neuroblastoma (NB) is the most common solid, extracranial childhood tumor. "RTL1 was one of 16 genes informative for survival time in a previous study of high-risk neuroblastomas, with stronger RTL1 expression associated with shorter survival." (PMID 39635126, 2024). "Taken together these findings suggest that upregulation of RTL1 in neuroblastoma is induced by bi-allelic activation in tumors with unfavorable prognosis, likely due to loss of imprinting on the maternal allele." (PMID 39635126, 2024). "Higher expression of RTL1 is thus suggestive of poor prognosis in neuroblastoma." (PMID 33245713, 2020). "Overall, we found that downregulation of 7 genes (Crb1, Lrrc9, Rcn1, Rtl1, Shisa3, Six6, St18) and upregulation of 2 genes (C1ql3, Slc18A1), are strongly predictive of favorable neuroblastoma outcome, consistent with delayed tumor development in Th-MYCN/Casp2−/− mice." (PMID 30670683, 2019).
virus infection (3 papers, 2015 to 2023). "In a new study in PLOS Biology, Nahid Shamandi, Matthias Zytnicki, Hervé Vaucheret, and colleagues show that in response to viral infection, one member of the group, RTL1, represses production of small RNAs." (PMID 26696554, 2015). "This ~20-fold increase in RTL1 mRNA accumulation was observed after individual infection with the four viruses, indicating that increased RTL1 expression is a general response to diverse virus infections." (PMID 26696443, 2015). "Our findings suggest that viruses have evolved to inhibit RTL1 activity, ultimately resulting in successful viral infection." (PMID 26696443, 2015). "The results above indicate that RTL1 expression is induced in response to virus infection, but that most viruses have evolved strategies to inhibit RTL1 activity, suggesting that RTL1 could be deleterious for virus replication." (PMID 26696443, 2015). "As such, RTL1 could target dsRNA intermediates of viral replication providing that RTL1 mRNA is induced during virus infection and RTL1 protein expressed where viruses replicate." (PMID 26696443, 2015). "We found that virus infection induces RTL1 expression, suggesting that this enzyme could play a role in plant–virus interaction." (PMID 26696443, 2015). "We also found that RTL1 expression is induced after virus infection, suggesting that RTL1 could act as an inducible antiviral defense by destroying dsRNA intermediates of viral replication." (PMID 26696443, 2015). "In otherwise healthy plants, overexpression of RTL1 suppressed production of small RNAs from over 6,000 loci, representing the vast majority of those examined, including multiple classes of small interfering RNAs (siRNAs), known for their roles in fighting viral infections." (PMID 26696554, 2015). "Here, the authors found that 2b, along with several other known VSRs, also inhibited RTL1, and plants overexpressing RTL1 fared no better than wild-type plants in fending off viral infection." (PMID 26696554, 2015). "The endogenous RTL1 gene is not expressed in Arabidopsis vegetative tissues, but is induced by various types of viruses, suggesting that RTL1 induction is a general response to virus infection." (PMID 36696453, 2023).
liver cancer (2 papers, 2017 to 2021). An epithelial or non-epithelial malignant neoplasm that arises from the liver. "Further, the expression of microRNAs in the exon of RTL1 is increased, and RTL1 is highly expressed in mouse liver cancer induced by the Sleeping Beauty (SB) gene." (PMID 29285312, 2017). "Because RTL1 is the only consistently altered gene detected in all SB-induced tumours with Dlk1-Dio3 integrations, it has been suggested that RTL1 activation is a driver of liver cancer." (PMID 29285312, 2017).
lung adenocarcinoma (2 papers, 2018 to 2022). A carcinoma that arises from the lung and is characterized by the presence of malignant glandular epithelial cells. "In the K mouse model of lung adenocarcinoma, the Dlk1-Dio3 locus, including the miRNA cluster and Rtl1, Meg3 and Dlk1, was found upregulated in lung tumors compared to normal lung tissue." (PMID 30190790, 2018).
lung carcinoma (2 papers, 2017 to 2018). "The methylation level of the RTL1 promoter is significantly lower in lung cancer tissues than in normal lung tissues." (PMID 29285312, 2017). "Patients with lung cancer showed three deregulated protein-coding genes: one was hypermethylated (DIO3) and two were hypomethylated (DLK1 and RTL1)." (PMID 29435111, 2018).
anxiety disorder (1 paper, 2022). A category of psychiatric disorders which are characterized by anxious feelings or fear often accompanied by physical symptoms associated with anxiety. "RTL1/PEG11, which has been associated with anxiety disorders, is a retrotransposon-derived imprinted gene in the placenta." (PMID 35567414, 2022).
cervical cancer (1 paper, 2023). A primary or metastatic malignant neoplasm involving the cervix. "Meanwhile, the cervical cancer tissue with a lower level of EREG just harbored higher mutative frequencies of KNTC1 and RTL1." (PMID 37020674, 2023).
Emery-Dreifuss muscular dystrophy (1 paper, 2019). Emery-Dreifuss muscular dystrophy (EDMD) is characterized by muscular weakness and atrophy, with early joint contractures and cardiomyopathy. "RTL1 protein was also detected in the regenerating myofibers of mdx muscle, as were transcripts in muscle biopsies from patients diagnosed with Emery-Dreifuss Muscular Dystrophy (AD-EDMD) caused by LMNA mutations, indicating that RTL1 expression may be a general requirement of muscle regeneration." (PMID 31686651, 2019).
Globozoospermia (1 paper, 2015). Any structural anomaly of the acrosome resulting in a round sperm head. "Six imprinted genes showed different 5hmC patterns between normal and abnormal sperm (GDAP1L1, GNAS, KCNK9, LIN28B, RB1, RTL1), and five imprinted genes showed different 5hmC patterns between normal and globozoospermia sperm (KCNK9, LIN28B, RB1, SLC22A18, ZDBF2)." (PMID 25762640, 2015).
hypothyroidism (1 paper, 2022). Abnormally low levels of thyroid hormone. "For instance, a loss of Grf1 or Dlk1 resulted in reduced GH content and secretion, while disruption of the imprinting domain encompassing Dlk1, Rtl1, and Dio3 resulted in transient perturbation in the GH/IGF-1 growth pathway with hypothyroidism." (PMID 35025875, 2022).
Infertility (1 paper, 2019). "In the Introduction, we have added discussion of polar overdominance and the callipyge phenotype of sheep, added references to antagonistic effects of MEGs and PEGs in fetal growth in mice and humans, and added references to the effects of RTL1 and associated microRNAs in infertility and cancer." (PMID 31640745, 2019). "Fourth, the authors should at least briefly discuss the roles of RTL1 in human disease, including infertility and cancer, and discuss how their proposed hypothesis may relate to disease susceptibilities and forms." (PMID 31640745, 2019).
intrauterine growth restriction (1 paper, 2023). "Abnormal expression of PEG11/RTL1 in humans has been associated with intrauterine growth restriction (IUGR), fetal anomalies, and death." (PMID 37842090, 2023).